APOB (apolipoprotein B)
Diseases named in the same sentence as APOB in open-access papers (continued):
Sharing a sentence is not in itself a finding about the gene and the disease.
Hypercholesterolemia (continued). "Lipid-lowering drugs with these two molecules as direct targets to complement the unmet need of familial hypercholesterolemia patients by conventional therapies include the small-molecule inhibitor of MTP, Lomitapide6, and the antisense oligonucleotide of APOB, Mipomersen7." (PMID 31098406, 2019). "Hypertriglyceridemia, hypercholesterolemia, high LDL-C, high TC/HDL-C, high non-HDL-C, high ApoB and mixed dyslipidemia were associated with poor glycemic control." (PMID 28376848, 2017). "Hypercholesterolemia, low HDL-C, high LDL-C, high TC/HDL-C, high non-HDL-C and high ApoB were associated with fasting hyperglycemia." (PMID 28376848, 2017). "In 2009, three novel drugs entered clinical evaluation, two of which, ALN-TTR01 and TKM-ApoB were SNALP-based delivery systems targeting hepatocytes and formulated with anti- Transthyretin (TTR) and anti-ApoB siRNAs in ATTR and hypercholesterolemia patients, respectively." (PMID 26056574, 2014). "It is characterized by hypertriglyceridemia, hypercholesterolemia, reduced high-density lipoprotein cholesterol (HDL-c), increased apolipoprotein B (apoB) and predominance of small, dense low-density lipoprotein (LDL) particles, features that are also present in conditions of insulin resistance." (PMID 24450309, 2014). "Some patients with hypercholesterolemia have no defect in LDL receptor, but have defective clearance of LDL due to mutations in ApoB gene." (PMID 22111029, 2012). "Individuals carrying ε2 allele have reduced risk for hypercholesterolemia (OR: 0.27, 95% I.C.: 0.08-0.85, p < 0.05) and NL ε2 carriers had lower total and LDL cholesterol and apoB levels, and higher HDL cholesterol than non-carriers (p < 0.05)." (PMID 22074026, 2011). "By contrast, APOB mutation carriers lacked xanthelasma, implying a lower cumulative LDL exposure, yet those who did develop CVD demonstrate that even moderately severe lifelong hypercholesterolemia can cause arterial disease over time." (PMID 41398288, 2025). "There was a trend toward a higher proportion of APOB mutations in the CVD group (20% vs 6.7%), indicating that even the “milder” familial hypercholesterolemia from APOB variants can lead to premature CVD if not adequately treated or if other risk factors are present." (PMID 41398288, 2025). "To this end we analyzed the age, gender, incidence of tendon xanthomas, BMI, family history of hypercholesterolemia, and blood lipid levels in each of these groups of patients and found that patients with positive genetic results presented with elevated TC, LDL-C, ApoB, and Lp (a)." (PMID 36991406, 2023).
Hypercholesterolemia (continued). "With regards to lipidic parameters, all of them (LDL-C, HDL-C, TG, apoB and apoA1) were significantly higher in subjects with hypercholesterolemia, compared to non-hypercholesterolemic individuals (p < 0.001, for all); even though there was a relatively wide standard deviation in both groups." (PMID 29295555, 2017). "For example Kynamro, an antisense inhibitor of apolipoprotein B, the principal apoprotein present on all atherogenic lipids, was approved by the FDA in January 2013 for use as an adjunct to first-line lipid-lowering therapies in homozygous familial hypercholesterolemia." (PMID 24803739, 2014). "Indeed, the young transgenic mice had higher concentrations of TC, FC, EC, LDL and apoB (but not HDL) than the aged wild-type mice, indicating that their genetic background is linked to a more dramatic hypercholesterolaemia than that seen in normal aging." (PMID 21829488, 2011). "Age greater than 45 y, waist circumference greater than 95/82 cm, fasting blood glucose greater than 100 mg/dl and apolipoprotein B levels greater than 100 mg/dl, were the most significant determinants of hypercholesterolemia, irrespective of lifestyle habits and other potential confounders." (PMID 18377643, 2008). "The estimated prevalence of severe hypercholesterolaemia (values above the P90) in the Portuguese population was as follows: TC = 30.1%, LDL-C = 30.3%, apoB = 30.4%, sdLDL-C = 31.3%, non-HDL-C = 29.8%, and Lp(a) = 13.1%." (PMID 39598108, 2024). "In 2013, the Food and Drug Administration (FDA) approved mipomersen as an adjunct to lipid-lowering therapy and dietary modifications to lower LDL-C, ApoB, and non-HDL-C in patients diagnosed with homozygous familial hypercholesterolemia (HoFH)." (PMID 38542510, 2024). "Improvements were also observed in hypercholesterolemia, in which significant decreases in serum total cholesterol, non-high-density lipoprotein (non-HDL) cholesterol, apolipoprotein A-1, and apolipoprotein B levels were observed." (PMID 30513715, 2018). "Among all individuals undergoing lipid-lowering therapy for hypercholesterolaemia (23.0% CI = [20.9–25.1%]), 55.9% had TC levels below 190 mg/dL; 60.4% had LDL-C levels below 116 mg/dL; 69.6% had apoB levels below 100 mg/dL; and 54.4% had non-HDL-C levels below 130 mg/dL." (PMID 39598108, 2024).
coronary artery disease (274 papers, 2007 to 2026). "Elevated ApoA1 levels are associated with decreased risk of coronary diseases, while high ApoB levels and high ApoB/ApoA1 ratios were related to increased cardiovascular events." (PMID 41601590, 2026). "In multivariate Mendelian randomization analyses, the associations of triglyceride and LDL-C levels with risk of coronary heart disease became null after adjustment for ApoB." (PMID 41030852, 2025). "Based on another study conducted in China, the ApoB:ApoA1 ratio was a more effective predictor of coronary heart disease risk in overweight and obese individuals than traditional lipid measures like LDL-C." (PMID 40944180, 2025). "The ratio of ApoB to apoA1 (ApoB/apoA1) is frequently used as a marker to assess the risk of coronary heart disease associated with lipoproteins." (PMID 40678973, 2025). "Previous studies have established a link between elevated ApoB levels and a heightened risk of coronary heart disease and other ischemic CVDs." (PMID 40678973, 2025). "Consistently, Mendelian randomization analyses identified ApoB as the top causal lipid-related factor for coronary artery disease (CAD), the most prevalent form of cardiovascular disease (CVD)." (PMID 40429957, 2025). "Apolipoprotein B (ApoB) comes in two isoforms (ApoB48 and ApoB100) in human plasma and serum, and its levels are correlated with the risk of coronary heart disease." (PMID 39104552, 2024). "While the link between total cholesterol and the risk of coronary artery disease is inconsistent, there is strong evidence linking low-density lipoproteins (especially ApoB) to coronary artery atherosclerosis." (PMID 39027784, 2024). "Concentrations of Chol, TG, ApoB, and ApoA1, are associated with coronary heart disease and carotid plaques." (PMID 38895187, 2024). "This genetic association study using mendelian randomization examines the association of various lipids (apolipoprotein B, low-density lipoprotein cholesterol, and triglycerides) with coronary artery disease and mortality outcomes." (PMID 38241044, 2024). "The immune response to these ApoB epitopes is proposed to be associated with the severity of coronary artery disease." (PMID 38393015, 2024). "As such, the apoB/apoA ratio (correspondently as LDL/HDL) is a strong predictor of coronary heart disease risk." (PMID 37484967, 2023). "Apolipoprotein B (ApoB) was considered to be the main lipoprotein component that leads to the risk of peripheral artery disease and coronary artery disease." (PMID 37047284, 2023). "Lipoprotein-associated ApoC-III [apoB, apoAI, Lp(a)] levels have been associated to coronary artery disease (CAD) risk in the EPIC-Norfolk prospective population study including 25,663 subjects." (PMID 36689070, 2023). "A retrospective case-cohort study, which included 1058 diabetic patients, aimed to evaluate the association between a low LDL-C/apoB ratio and the presence of coronary heart disease (CHD)." (PMID 37629496, 2023). "Large differences were identified when comparing top and bottom deciles; for example, using the apolipoprotein B polygenic risk scores there was a mean difference of 13.2 mg/dL for this established risk factor of coronary heart disease in later life." (PMID 35045726, 2022). "In multivariable Mendelian randomization analyses, the associations of levels of triglyceride and LDL-C with the risk of coronary heart disease became null after adjusting for apoB." (PMID 35573992, 2022). "In another study of Ference, the association of the levels of triglycerides and LDL-C with the risk of coronary heart disease was proportional to the absolute change in apoB." (PMID 35573992, 2022).
coronary artery disease (continued). "The subgroup with high urinary excretion without kidney stress (HR = 1.24) and the subgroup with the highest apolipoprotein B and blood pressure (HR = 1.52) were associated with ischemic heart disease (IHD)." (PMID 35597771, 2022). "Our colocalization analysis using cis-mQTL variants for CpGs and GWAS summary statistics of these variants for CAD identified colocalization of an LDL-associated CpG, cg05337441 (APOB), with coronary artery disease." (PMID 36380121, 2022). "Apolipoprotein B is being increasingly acknowledged as a main contributor to atherosclerotic CVD, and large cohorts studies of have found oxidized lipids like Apolipoprotein B to be associated with coronary artery disease." (PMID 36503487, 2022). "Analyzing the reasons for this, there is ample evidence that lowering apoB levels significantly reduces the risk of coronary heart disease." (PMID 35573992, 2022). "Carrying a heterozygous APOB (He-APOB) PTC was associated with a significantly lower risk for coronary heart disease." (PMID 35457099, 2022). "This study interrogated the relationship between IgM and IgG anti-ApoB autoantibodies in patients with coronary artery disease (CAD) and traditional cardiometabolic risk factors." (PMID 35479271, 2022). "Meanwhile, genetic mutations of APOB are also associated with the risk of coronary artery diseases and CD." (PMID 36114174, 2022). "Plasma ApoB and ApoAI are also reported to be stronger risk factors for coronary artery disease (CAD) than LDL and HDL." (PMID 34674306, 2021). "According to epidemiological research, the ratio of APOA1 to APOB was a good predictor of coronary heart disease risk." (PMID 34702323, 2021). "In conclusion, our evaluation of apoB using outcomes in first-degree relatives identified that higher apoB is detrimental to lifespan and increases the risk of coronary heart disease and type 2 diabetes." (PMID 34729547, 2021). "APOE genetic variants also affect apolipoprotein B (apoB), whose relevance to ischemic heart disease (IHD) is increasingly acknowledged." (PMID 34203181, 2021). "ApoB/apoA1 can be used as a predictor of coronary heart disease risk, but its effect on prognosis of ACS patients is rarely reported." (PMID 32539722, 2020). "HDL and its major protein ApolipoproteinA1 (ApoA1) are recognized as independent protective factors against coronary heart disease, while elevated Apolipoprotein B (ApoB), LDL and TG are associated with a higher risk of atherosis and cardiovascular disease." (PMID 32000699, 2020). "In another study on Russians,it was argued that ApoB genetic polymorphism affects the development of coronary heart disease by affecting the level of internal lipids." (PMID 32493216, 2020). "Higher apoB/apoA-I ratios were associated with more coronary arteries showing angiographically significant coronary artery disease and more lesion complexity." (PMID 32449038, 2020). "ApoB has been associated with increased coronary artery disease, while LGI diets have been shown to significantly reduce the risk." (PMID 32867226, 2020). "Many studies have shown that plasma apolipoprotein B concentration and its gene polymorphism are inextricably linked to the development of coronary heart disease." (PMID 32493216, 2020). "A meta-analysis of 23 prospective studies demonstrated that low apoA1 levels and high apoB and apoB/A1 levels were associated with an increased risk of coronary heart disease (CHD)." (PMID 29312456, 2018). "For example, DLAD4U linked the APOB gene to coronary disease with 819 supporting publications and a score of 1819." (PMID 30591010, 2018). "It has been shown that the apoB/apoA-I ratio is superior to any of the cholesterol ratios in predicting the risk of coronary disease." (PMID 30591010, 2018). "One additional APOB variant with strong associations with ischemic heart disease (rs5742904; OR = 7) was rare in every population analyzed." (PMID 30076208, 2018).
coronary artery disease (continued). "Our equation to predict apoB levels showed MCVE risk prediction comparable to directly-measured apoB in high risk patients with previous coronary heart disease." (PMID 28830468, 2017). "The association of the apoB/A-I ratio with coronary heart disease incidence in individuals with CKD, which was defined as an eGFR of 15 to <60 mL/min/1.73 m2, was similar to that observed for other lipid measurements in the population-based cohort study." (PMID 28957410, 2017). "As a consequence, HDL particle concentrations in the top quartile decreased coronary artery disease (CAD) risk by 50% relative to the bottom quartile following adjustment for plasma apoB and triglyceride levels." (PMID 26500551, 2015). "Decreasing the TG /HDL-c and apoB/ apoA-I in our study means that the small dense LDLs are decreased significantly and coronary artery disease and myocardial infarction risk in BRFE group is much lower than control one." (PMID 24250489, 2012). "It is well-known that the apoB/apoA-I ratio is important to predict the risk of coronary artery disease (CAD)." (PMID 22211242, 2012). "As the elevation of the concentration of apoB as well as of LDL cholesterol is regarded as an important risk factor for coronary artery disease." (PMID 18925970, 2008). "These authors reported that apoB was consistently a stronger predictor of coronary heart disease risk, as well as peripheral and coronary atherosclerosis, than either non-HDL cholesterol or LDL-C." (PMID 19690648, 2007). "In the existing literature, there is no hard evidence as yet regarding the possible effects of inflammation on apoB levels or the association between apoB and coronary artery disease." (PMID 19690648, 2007). "However, the Quebec Cardiovascular Study demonstrated that the 5‐year risk of coronary artery disease in individuals with disproportionately elevated apoB levels was comparable to that observed in individuals with disproportionately elevated LDL‐C levels." (PMID 40386959, 2025). "Angina, BNP, HbA1c, ApoB,D-dimer, and Fg were among the risk factors for coronary artery disease." (PMID 39867191, 2025). "Therefore, elevated ApoB is strongly associated with greater risk of coronary artery disease, even if LDL levels are normal." (PMID 40944180, 2025). "Lipoprotein (a) (Lp(a)) - an LDL-like particle containing apolipoprotein B (apoB) with an additional protein, apolipoprotein (a) (apo(a)) - has been identified as a causal factor for coronary heart disease (CHD) based initially on epidemiological findings and most recently on genetic studies 1–3." (PMID 38233012, 2024). "And High ApoB is a risk factor for coronary heart disease and arteriosclerosis, which may be a link between these and PTB." (PMID 38734779, 2024). "However, some studies have shown that ApoB/ApoA-I is a better indicator of cholesterol balance than traditional lipid markers, especially in predicting the risk of ischemic events such as coronary heart disease, myocardial infarction, and ischemic stroke." (PMID 38274879, 2023). "Our study also suggests that pregnant women with elevated levels of Lp(a) and ApoB may be predisposed to coronary disease at an earlier age." (PMID 37763183, 2023). "Furthermore, case-control studies comprising 57973 individuals demonstrated an association between ApoB truncation and a decreased incidence of coronary heart disease." (PMID 38260151, 2023). "For example, in the analysis regarding apolipoprotein B, a risk factor for coronary artery disease in later life, the mean measure among participants allocated to the top decile was 65.4 mg/dL, which was markedly different to the mean level of those grouped in the bottom decile (52.6 mg/dL)." (PMID 35045726, 2022). "Moreover, on multivariable MR of lipid indices, a causal relationship was only retained for ApoB, consistent with the suggestion from another recent multivariable MR that ApoB underlies the relationship between lipid traits and coronary heart disease risk." (PMID 34542150, 2022).